HACE1 (HECT domain and ankyrin repeat containing E3 ubiquitin protein ligase 1)
Diseases named in the same sentence as HACE1 in open-access papers (continued):
Sharing a sentence is not in itself a finding about the gene and the disease.
glioma (3 papers, 2021 to 2025). A benign or malignant brain and spinal cord tumor that arises from glial cells (astrocytes, oligodendrocytes, ependymal cells). "Further studies reveal that HACE1 causes enhanced malignant phenotypes and decreased radiosensitivity of glioma cells by activating nuclear factor erythroid 2-related factor 2 (NFE2L2, also known as NRF2) via multiple mechanisms." (PMID 34815381, 2021). "Considering that high invasiveness/metastasis ability of glioma cells is a major cause for a high incidence of recurrence, meaning a worse patient survival, we thus investigated the influence of HACE1 on the migration and invasion of U87 and SF295 cells." (PMID 34815381, 2021). "In summary, the present study demonstrates the oncogenic role of HACE1 in glioma cells, and determines that HACE1 causes enhanced malignant phenotypes and decreased radiosensitivity of glioma cells by enhancing protein stability and IRES-mediated mRNA translation of NRF2." (PMID 34815381, 2021). "Altogether, our data demonstrate that HACE1 causes enhanced malignant phenotypes and decreased radiosensitivity of glioma cells by activating NRF2, and indicate that it may act as the role of prognostic factor and potential therapeutic target in glioma." (PMID 34815381, 2021). "As expected, we found that overexpression of HACE1 in glioma cells substantially enhanced the ability of cell proliferation and invasiveness compared with the control, and these effects were effectively attenuated upon NRF2 knockdown." (PMID 34815381, 2021). "To determine the role of HACE1 in glioma cells, we first designed two different siRNAs targeting HACE1 (siHACE1-1 and siHACE1–2), and validated their knockdown efficiency in U87 and SF295 cells." (PMID 34815381, 2021). "This was supported by our data that HACE1 overexpression decreased the sensitivity of glioma cells to radiotherapy compared to the control." (PMID 34815381, 2021). "We first determined HACE1 expression by immunohistochemistry and western blot assays, and found that elevated expression of HACE1 in gliomas compared to normal brain tissues (control subjects)." (PMID 34815381, 2021). "HACE1 knockdown obviously suppressed malignant behaviors of glioma cells, while ectopic expression of HACE1 enhanced cell growth in vitro and in vivo." (PMID 34815381, 2021). "Second, by a series of functional experiments, we demonstrated that HACE1 exerted an oncogenic function in glioma cells through enhancing malignant behaviors of glioma cells in an E3 ligase-independent manner." (PMID 34815381, 2021). "Next, we established an orthotopic rat glioma model by injecting HACE1 overexpression-C6 cells and control cells." (PMID 34815381, 2021). "We first observed elevated expression of HACE1 in gliomas compared with normal brain tissues, and a close correlation between high HACE1 expression and poor prognosis in patients with WHO grade III and IV." (PMID 34815381, 2021). "HACE1, for instance, promotes malignant progression and radiotherapy resistance in glioma by competitively binding to NRF2 with KEAP1, thereby enhancing NRF2 stability and IRES‐dependent upregulation of NRF2 translation levels, leading to a significant decrease in intracellular ROS levels." (PMID 40583858, 2025). "To determine whether HACE1 affects the response of glioma cells to radiation, we ectopically expressed HACE1 in SF295 and C6 cells, and treated these cells with radiation." (PMID 34815381, 2021). "Through clinical data analysis, we speculate that HACE1 may affect the radiosensitivity of glioma patients." (PMID 34815381, 2021). "Thus, our results support the notions that HACE1 is considered as a prognostic factor and potential therapeutic target in glioma, and targeting HACE1 may be therapeutically beneficial in glioma patients." (PMID 34815381, 2021). "Therefore, we speculate that HACE1 enhances malignant phenotypes of glioma cells probably by regulating NRF2 activity." (PMID 34815381, 2021).
glioma (continued). "By analyzing the RNA-Seq data set from the Chinese Glioma Genome Altas (CGGA), we found that high HACE1 expression clearly reduced the survival in patients with WHO grade III and IV." (PMID 34815381, 2021). "Considering that HACE1 is able to activate NRF2, a key oncoprotein in glioma, under oxidative stress, thus we determined the regulatory effect of HACE1 on NRF2 activity, attempting to illustrate its oncogenic role in glioma cells." (PMID 34815381, 2021). "Finally, we demonstrated that HACE1 dramatically reduced cellular ROS levels by activating NRF2, thereby decreasing the response of glioma cells to radiation." (PMID 34815381, 2021). "Due to the limited number of samples, we did not investigate the correlation of HACE1 expression with the survival of high-grade glioma (HGG) patient receiving radiotherapy." (PMID 34815381, 2021). "Here, we observed increased expression of HACE1 in gliomas related to control subjects, and found a strong correlation of high HACE1 expression with poor prognosis in patients with WHO grade III and IV as well as low-grade glioma (LGG) patients receiving radiotherapy." (PMID 34815381, 2021). "Our data showed that HACE1 post-transcriptionally upregulated NRF2 expression via an E3 ligase-independent mechanism, and demonstrated that HACE1 promoted malignant behaviors of glioma cells through activating NRF2." (PMID 34815381, 2021). "Notably, HACE1 not only increased La/SSB expression, but also impaired its nuclear/cytoplasm distribution, as supported by our data that HACE1 interacted and co-localized mostly with La/SSB in the extranuclear region of glioma cells." (PMID 34815381, 2021).
Ataxia (2 papers, 2021 to 2022). Ataxia refers to impaired coordination of voluntary muscle movement. "Our results have identified a new phenotype associated with HACE1 and provide a novel candidate gene for non-syndromic cerebellar ataxia." (PMID 35061740, 2022). "We therefore suggest that the spontaneous HACE1 mutation in dog may serve as an attractive model for ataxia in human." (PMID 35061740, 2022). "The guanine-deletion (62,282,767delG) identified in HACE1 of the NEB ataxia-cases disrupts the reading frame and alters the primary structure of the protein." (PMID 35061740, 2022). "Since HACE1 mutations are associated with a syndrome in human (SPPRS) and we found no indication (post-mortem and CT) that other organs were affected in the NEB cases, we have called this a non-syndromic form of ataxia." (PMID 35061740, 2022). "This makes HACE1 a novel candidate gene for ataxia and cerebellar dysfunction." (PMID 35061740, 2022).
developmental delay (2 papers, 2022 to 2024). "Here, we report a rare missense variant (c.350T>C; p.(Leu117Ser)) in HACE1 segregating with NDD syndrome with clinical features including ID, epilepsy, spasticity, global developmental delay, and psychomotor impairment in two siblings of a consanguineous Pakistani kindred." (PMID 38790209, 2024). "The human neurological disease caused by mutations in HACE1, SPPRS, is typically characterized by hypotonia, progressive spasticity of the lower limbs, global developmental delay, mental retardation, speech difficulty, and seizures, as well as various congenital abnormalities." (PMID 35061740, 2022).
Ewing sarcoma (2 papers, 2019 to 2021). A small round cell tumor that lacks morphologic, immunohistochemical, and electron microscopic evidence of neuroectodermal differentiation. "To confirm that HACE1 tumor suppressor activity is linked to its ability to reduce HIF1α levels, we performed soft agar colony assays using the SKNEP1 human Ewing sarcoma cell line that lacks endogenous expression of HACE1." (PMID 33603169, 2021).
Intellectual disability (2 papers, 2019 to 2022). "Nonetheless, via whole exome sequencing in 2015, HACE1 mutations were suggested to be the cause of a new autosomal recessive neurodevelopmental disorder, which is characterized by spasticity, muscular hypotonia, and intellectual disability." (PMID 36553453, 2022). "The second notable clinical feature of SPPRS patients is intellectual disability.5, –, 7 To determine whether learning and memory processes are altered in Hace1 KO animals, we analyzed mutant mice in various hippocampal-dependent behavioral tasks." (PMID 31321300, 2019).
ovarian carcinoma (2 papers, 2011 to 2019). A malignant neoplasm originating from the surface ovarian epithelium. "FISH on a TMA of 239 ovarian tumours, including 73 of known molecular subtype found evidence for rearrangement between HACE1 and LIN28B in only a single core from a HG-SOC tumour of unknown molecular subtype, suggesting this mechanism for LIN28B up-regulation is rare in ovarian carcinoma." (PMID 21533284, 2011).
sarcoma (2 papers, 2019 to 2021). A usually aggressive malignant neoplasm of the soft tissue or bone. "Consistent with this, genetic inactivation of HACE1 in mice leads to the development of multiple late-onset tumors, including sarcomas, breast, lung, and other carcinomas, as well as lymphomas." (PMID 33603169, 2021).
3-methylglutaconic aciduria (1 paper, 2022). A group of five inherited disorders caused by mutations in the AUH, DNAJC19, OPA3, and TAZ genes. "Recently, HACE1 mutations were identified in a patient with severe psychomotor- and mental retardation, diffuse cortical atrophy and 3-methylglutaconic aciduria." (PMID 35061740, 2022).
Brain atrophy (1 paper, 2020). Partial or complete wasting (loss) of brain tissue that was once present. "Whole-exome sequencing identified homozygous HACE1 mutations (c.240C>A, p.Cys80Ter) in a patient with brain atrophy, psychomotor retardation and 3-methylglutaconic aciduria, a biomarker of mitochondrial dysfunction." (PMID 32225089, 2020). "We report a patient carrying HACE1 mutations presenting with psychomotor retardation, brain atrophy and high urinary excretion of 3-methylglutaconic acid (3-MGA), a well-established biomarker of mitochondrial dysfunction." (PMID 32225089, 2020). "Here, we report on a patient with psychomotor retardation, brain atrophy and 3-MGA-uria carrying a previously reported homozygous mutation (c.240C>A; p.Cys80Ter) in HACE1, which encodes for a HECT domain and ankyrin repeat-containing ubiquitin ligase protein." (PMID 32225089, 2020).
breast tumor (1 paper, 2015). "Here, using an insertional mutagenesis screen in mammary epithelial cells that express wild-type neu, we identify and establish HACE1 as a breast tumor suppressor gene that attenuates the levels of activated Rac1." (PMID 25659579, 2015).
COVID-19 (1 paper, 2023). A disease caused by infection with severe acute respiratory syndrome coronavirus 2. "RBD binding to hACE2 shifts the hACE2/hACE1 balance towards Ang 2 generation, the circulating levels of which are increased in severe COVID-19 patients." (PMID 37638055, 2023).
depression (1 paper, 2020). "Lower DNAm at cg02098413 located in the HACE1 promoter conferred by the risk allele (C allele) at rs1933802 was associated with higher risk for depression (praw = 0.014, DNAm = 2.3%)." (PMID 32616021, 2020). "We present a genotype-dependent DNAm at the HACE1 gene that associates with depression in brain and whole blood across diverse datasets, specifically adolescents at risk for depression and adults diagnosed with MDD." (PMID 32616021, 2020). "Higher DNAm at cg02098413 located upstream of HECT Domain and Ankyrin Repeat Containing E3 Ubiquitin Protein Ligase 1 (HACE1) was associated with lower depression score (praw = 0.014, odds ratio (OR) = 0.23)." (PMID 32616021, 2020). "Alterations at HACE1 and SHANK2 loci imply potential mechanisms, such as oxidative stress in the brain, underlying depression." (PMID 32616021, 2020). "Our findings suggest that lower HACE1 expression levels in the CA1 hippocampal region of adults diagnosed with major depression might lead to dendritic damage via increased ROS." (PMID 32616021, 2020). "Our results are strengthened by our comprehensive bioinformatics analysis that is integrating multiple lines of evidence point at a role for HACE1 and SHANK2 in the pathophyology of depression." (PMID 32616021, 2020).
gastric tumor (1 paper, 2018). "And in vivo, the tumor xenograft study provided a further exhibition of HACE1's function as inhibiting the growth of gastric tumor in nude mice." (PMID 29673126, 2018).
heart failure (1 paper, 2023). Inability of the heart to pump blood at an adequate rate to meet tissue metabolic requirements. "HACE1-mediated ubiquitinated proteins interact with ankyrin domain proteins, facilitating selective autophagy of heart failure-related cells, underscoring its pivotal role in cardiac protection." (PMID 38070140, 2023). "The results revealed a significant down-regulation of HACE1 in the heart failure patients, suggesting its possible involvement in the disease." (PMID 38070140, 2023). "Expression of the HACE1 protein was detected in heart tissue samples from the heart failure mice model." (PMID 38070140, 2023). "Heart failure patients exhibit elevated serum HACE1 levels, which help control protein degradation and safeguard the heart from hemodynamic stress." (PMID 38070140, 2023). "This study aimed to investigate the role of HACE1 in heart failure and its potential therapeutic applications." (PMID 38070140, 2023). "As per these findings, the HACE1 was found to be one of the crucial regulatory genes that mitigate the oxidative stress in case of heart failure model." (PMID 38070140, 2023). "In response to hemodynamic changes sensed in cardiac tissues, HACE1 acts to protect against heart failure through cardiac protection mechanisms." (PMID 38070140, 2023). "Furthermore, in-vivo experimentation on mice showed that down-regulation of HACE1 using shRNA aggravated heart failure and enhanced oxidative stress." (PMID 38070140, 2023). "In current study, an inhibitory effect was expressed by HACE1 mRNA in heart failure model." (PMID 38070140, 2023). "Through current study results, NRF2 was identified as a target for HACE1 in heart failure model." (PMID 38070140, 2023). "By ubiquitination, the HACE1 boosted the activity levels of NRF2 in heart failure model." (PMID 38070140, 2023). "HACE1 mRNA was up-regulated in mice with heart failure after 2-4 weeks of induction (p < 0.05)." (PMID 38070140, 2023). "HACE1 mRNA expression was significantly inhibited in heart failure patients (p < 0.05)." (PMID 38070140, 2023). "Recent studies suggest that HACE1, a regulatory gene, may be involved in cardiac protection against heart failure." (PMID 38070140, 2023). "The current study outcomes confirm the promotion of NRF2’s activities by HACE1, while the latter inhibited the ubiquitination of the former in order to mitigate the mitochondrial damage and ferroptosis by inactivating the ROS-oxidative stress in heart failure model." (PMID 38070140, 2023). "However, the Sh-HACE1 tend to aggravate the heart failure problem in mice model." (PMID 38070140, 2023). "The study reveals that HACE1 achieves these effects, at least in part, through NRF2 activation via ubiquitination, offering insights into novel mechanisms for heart failure pathogenesis and potential interventions." (PMID 38070140, 2023). "Knockdown of HACE1 via si-HACE1 decreased ROS and MDA levels (p < 0.05) but increased SOD, GSH, and GSH-PX levels (p < 0.05) in the in vitro heart failure model." (PMID 38070140, 2023). "Up-regulation of HACE1 via HACE1 plasmid increased ROS and MDA levels (p < 0.05) but reduced SOD, GSH, and GSH-PX levels (p < 0.05) in the in vitro heart failure model." (PMID 38070140, 2023). "The study compared the expression levels of HACE1 between heart failure patients (experimental group) and normal individuals (normal group)." (PMID 38070140, 2023). "HACE1 knockdown led to decreased cell viability, increased PI-positive cells and iron concentration (p < 0.05), and reduced GPX4 expression (p < 0.05) in the in vitro heart failure model." (PMID 38070140, 2023). "Up-regulation of HACE1 enhanced cell viability and promoted calcien-AM/CoCl2 levels (p < 0.05), reduced LDH activity and IL-1α levels (p < 0.05), and decreased PI-positive cells and iron concentration (p < 0.05) in the in vitro heart failure model." (PMID 38070140, 2023).
heart failure (continued). "Mice with defective HACE1 expression display abnormal myocardial hypertrophy, left ventricular dysfunction, and the accumulation of autophagy-related proteins LC3 and p62, indicating disrupted autophagy processes that exacerbate heart failure and increase mortality rates." (PMID 38070140, 2023). "A negative correlation was observed between HACE1 serum expression levels and collagen I (p < 0.05) and collagen III (p < 0.05) in heart failure patients." (PMID 38070140, 2023).
invasive ductal breast carcinoma (1 paper, 2015). The most common type of invasive breast carcinoma, accounting for approximately 70% of breast carcinomas. "Interestingly, HACE1 expression was also highly significantly underexpressed in all invasive ductal breast carcinoma compared with normal breast, suggesting that HACE1 loss is not confined to HER2 positivity." (PMID 25659579, 2015). "Moreover, allelic loss of HACE1 in invasive ductal breast carcinoma was also observed in the TCGA breast data set." (PMID 25659579, 2015). "HACE1 was found to be highly significantly underexpressed in HER2+ invasive ductal breast carcinoma compared with normal breast epithelium." (PMID 25659579, 2015).
megacolon (1 paper, 2020). "Since our 4C-seq analysis identified many gains and losses of chromatin contacts with the Hace1-Grik2 silencer-enriched region, we surmised that the TashT transgene insertion event causing the megacolon phenotype interferes with normal chromatin interactions and/or triggers new ectopic interactions." (PMID 32898154, 2020).
NK/T cell lymphoma (1 paper, 2015). "Other reports also indicated that the expression of HACE1, ATG5, and AIM1 was decreased in NK/T cell lymphoma, although the research is limited." (PMID 26221594, 2015). "The deletion of 6q21 has been identified as the common genetic aberration in NK/T cell lymphoma (20–43%), and the genes located in the region of 6q21, including POPDC3, PREP, PRDM1, ATG5, AIM1, HACE1, and FOXO3, were reasonably considered the affected candidates." (PMID 26221594, 2015).
oncocytoma (1 paper, 2024). "In a study aimed at distinguishing ChRCC from RO, the genes LMBRD1, TPBG, MANEA, and HACE1 were integral components of a 30-gene signature known as chromophobe and oncocytoma-related gene signature (COGS)." (PMID 39684226, 2024).
paraplegia (1 paper, 2022). Complete paralysis of the lower half of the body including both legs, often caused by damage to the spinal cord. "However, gross deletions in the HACE1 gene have not yet been mentioned as a cause of spastic paraplegia." (PMID 36553453, 2022). "Spastic paraplegia and psychomotor retardation with or without seizures (SPPRS, OMIM 616756) is a rare genetic disease caused by biallelic pathogenic variants in the HACE1 gene." (PMID 36553453, 2022). "Spastic paraplegia and psychomotor retardation with or without seizures (OMIM 616756) is an autosomal recessive disorder caused by the presence of two mutations in the HACE1 gene in trans." (PMID 36553453, 2022).
Retinal dystrophy (1 paper, 2015). Retinal dystrophy is an abnormality of the retina associated with a hereditary process. "It is therefore possible that the retinal dystrophy and macular hypoplasia that are present in four of our eight patients relate to a loss of Rac1 regulation by HACE1." (PMID 26424145, 2015).
Ureteral obstruction (1 paper, 2024). Obstruction of the flow of urine through the ureter. "When we assessed the levels of Hace1 in our murine model, we found it to be up-regulated in irreversible but not in reversible ureteral obstruction." (PMID 38324689, 2024).